GRIK3 (glutamate ionotropic receptor kainate type subunit 3)
Diseases named in the same sentence as GRIK3 in open-access papers:
GRIK3 is named in the same sentence as 46 diseases in open-access papers, as found by Europe PMC text mining. Sharing a sentence is not in itself a finding about the gene and the disease. The quoted sentences say what the papers report.
schizophrenia (13 papers, 2008 to 2025). A major psychotic disorder characterized by abnormalities in the perception or expression of reality. "GRIK3 encodes a glutamate receptor and has previously been associated with mental disorders, particularly schizophrenia." (PMID 37953886, 2023). "A splice variant within GRIK2 6:102337505, c.1525–10 C > T (p = 4.43 × 10−8; OR = 42.26, CI 2.53–704) and a missense variant within GRIK3, R865G, (p = 6.8 × 10−6; OR = 73, CI 4–1226) showed a significant nominal association with risk for schizophrenia." (PMID 31844109, 2019). "It is highly significant in both LS and mPFC arrays, while other glutamate-related genes strongly linked to schizophrenia, such as the kainate receptor 3 (Grik3), and metabotropic glutamate receptors 5 and 7 (Grm5, and Grm7), are only significant in mPFC." (PMID 24765068, 2014). "In addition to the significant change of Grik3 mRNA expression in the present study, a relationship between GRIK3 polymorphisms and increased schizophrenia risk was reported in a previous study." (PMID 37860710, 2023). "Moreover, meta-analyses have reported that polymorphisms of GRIK3, the principal subunit of the kainate-type ionotropic glutamate receptor, increased schizophrenia risk by 30 %." (PMID 37860710, 2023). "We performed an association study between the Ser310Ala GRIK3 polymorphism and schizophrenia in a sample of 100 schizophrenic patients and 100 controls and 50 patient controls (neuropsychiatric patients other than schizophrenics) in Indian population by PCR-RFLP." (PMID 21593965, 2008). "After resequencing 516 unrelated patients with schizophrenia, 44 protein-altering variants were identified, including 12 in the GRIK1, 5 in the GRIK2, 7 in the GRIK3, 13 in the GRIK4, and 7 in the GRIK5." (PMID 35629206, 2022). "Therefore, we sequenced the exonic regions of five kainate receptor genes (GRIK1, GRIK2, GRIK3, GRIK4, and GRIK5) to identify rare pathogenic variants in patients with schizophrenia using the ion semiconductor sequencing method." (PMID 35629206, 2022). "However, several VMPs exhibited opposite patterns of variance between blood and brain regions, including some within the GRIK3, GFI1, ADRB3 and MND1 genes, amongst others, indicating that some schizophrenia associated VMPs may exhibit divergent variance patterns between the periphery and brain." (PMID 39271751, 2025).
breast carcinoma (5 papers, 2013 to 2024). "GRIK3 has been reported to be associated with breast cancer and is also in consideration for diagnostic value in lung cancer." (PMID 24369052, 2013). "GRIK3 was correlated with breast cancer and being considered as diagnostic for lung cancer." (PMID 24369052, 2013). "For instance, GRIK3 expression is prominent in breast cancer tissues, and it increases proliferation and migration of breast cancer cells in vitro, driving epithelial-to-mesenchymal transition." (PMID 38788724, 2024). "GRIK3 promotes epithelial-mesenchymal transition by regulating the SPDEF/CDH1 signaling in breast cancer cells." (PMID 33717664, 2021). "In the present study, we sought to gain new insights into the role of GRIK3 in the progression and development of breast cancer." (PMID 30977227, 2019). "Heterogenous expression of SPDEF and CDH1 counteracted the migration and invasion abilities, respectively, of breast cancer cells induced by GRIK3." (PMID 30977227, 2019). "GRIK3 promoted the proliferation and migration abilities of breast cancer cells and enhanced the growth of orthotopically implanted tumors." (PMID 30977227, 2019). "The KEGG analysis revealed that GRIK3 affected several key signaling pathways in breast cancer, such as the Notch signaling pathway and Jak‐STAT signaling pathway." (PMID 30977227, 2019). "On the basis of these results, we concluded that GRIK3 is involved in the tumorigenesis of breast cancer." (PMID 30977227, 2019). "Taken together, these results indicate that SPDEF/CDH1 signaling is required for the GRIK3‐mediated cell proliferation, migration, and invasion of breast cancer cells." (PMID 30977227, 2019). "The present study is the first study suggesting that GRIK3 is an oncogene in breast cancer and is involved in the EMT pathway." (PMID 30977227, 2019). "GRIK3 expression was further examined in 140 breast cancer tissues and 90 paired adjacent non‐cancerous tissues using tissue arrays." (PMID 30977227, 2019). "Furthermore, the total protein was extracted from four paired breast cancer tissues and corresponding adjacent tissues, and GRIK3 expression was examined by Western blot." (PMID 30977227, 2019). "GRIK3 expression was also positively correlated with the prognosis of patients with breast cancer." (PMID 30977227, 2019). "Given the high expression level of GRIK3 in breast cancer tissues, we hypothesized that GRIK3 could be an oncogene." (PMID 30977227, 2019). "In this study, we provided evidence that the expression of GRIK3 is upregulated in breast cancer." (PMID 30977227, 2019). "Meanwhile, GRIK3, as a membrane receptor, may also serve as a potential therapeutic target for the treatment of breast cancer." (PMID 30977227, 2019). "Taken together, these results suggested that the mechanism underlying how GRIK3 was transcribed into mRNA and further translated into protein is complicated and requires further study, however GRIK3 expression at protein level could be served as a biomarker for breast cancer." (PMID 30977227, 2019). "The analysis of GRIK3 mRNA expression in five different breast cancer cell lines with different molecular classification and one normal breast cell line, MCF10A, showed higher GRIK3 mRNA levels in the five breast cancer cell lines." (PMID 30977227, 2019). "Our study aimed to reveal the expression and clinical significance of GRIK3 in breast cancer, explore further whether the overexpression of GRIK3 protein is a key step in the growth and metastasis of breast cancer, and explore the specific molecular mechanism GRIK3 affects breast cancer development." (PMID 30977227, 2019). "Here, we primarily reported that the expression of GRIK3 was higher in breast cancer tissues than in adjacent noncancerous tissues." (PMID 30977227, 2019).
breast carcinoma (continued). "Although the biological functions of GRIK3 in breast cancer have been exposed only slightly, additional research should be conducted into the mechanics of its oncogenic effects, such as how GRIK3 inhibits the expression of CDH1 and is the structure of the GRIK3‐centric protein interaction network." (PMID 30977227, 2019). "As the SPDEF/CDH1 pathway is involved in mechanisms regulating cell‐cell adhesions, mobility, and proliferation of epithelial cells and suppressed breast cancer metastasis through epithelial‐mesenchymal transition (EMT), we hypothesized that GRIK3 might play an important role in EMT." (PMID 30977227, 2019).
lung carcinoma (5 papers, 2013 to 2024). "GRIK3 is implicated in proliferation and migration of intestinal and lung cancer cells." (PMID 38788724, 2024).
depression (4 papers, 2018 to 2025). "The GRIK gene family (GRIK1, GRIK2, GRIK3, GRIK4, and GRIK5) has genetic variants associated with many psychiatric illnesses including; depression, obsessive–compulsive disorder, and autism." (PMID 41327126, 2025). "Among them, low-affinity KAR genes GRIK1, GRIK2, and GRIK3 are reported as one of the candidates for schizophrenia, mania, mild mental retardation, autism and major depression in the human genetic studies." (PMID 38402313, 2024). "The genes that are potentially of interest for the study of depression include the Neural Growth Regulator 1 (NEGR1), the glutamate metabotropic receptor 5 (GRM5), the glutamate ionotropic receptor kainate type subunit 3 (GRIK3) and the transmembrane protein 106B (TMEM106B) protein coding genes." (PMID 29662059, 2018).
developmental delay (3 papers, 2016 to 2022). "More precisely, GLUT1 deficiency may cause a specific syndrome which correlates with hyperactivity and developmental delay, RIMS3 is considered to be a novel candidate for autism, GRIK3 has also been associated with developmental delay, and AGO1/AGO3 may be responsible for neurocognitive deficits." (PMID 27713767, 2016).
gastric cancer (2 papers, 2019 to 2021). A primary or metastatic malignant neoplasm involving the stomach. "GRIK3 mainly participates in the neuroactive ligand–receptor interaction pathway, and GRIK3 upregulation is associated with poor survival in gastric cancer." (PMID 33717664, 2021).
glioma (2 papers, 2019 to 2023). A benign or malignant brain and spinal cord tumor that arises from glial cells (astrocytes, oligodendrocytes, ependymal cells). "The most notable lncRNA is LINC00599, which has DBSs in many NGS genes in most gliomas, including GABBR1, NRCAM, PTPRS, GLRB, GRIA4, GRIK3, and MAP2, and the most notable NGS gene is MAP2, which is associated with microtube assembly and regulated by multiple lncRNAs through the same DBS." (PMID 37693314, 2023).
neuroblastoma (2 papers, 2019). Neuroblastoma (NB) is the most common solid, extracranial childhood tumor. "The other RNAs considerably over-expressed in MYCN-amplified neuroblastoma cell lines were RP11-102F4.3, RNF217, GRIK3, and SLCO5A1." (PMID 31690716, 2019). "Here our RNA sequencing analysis identifies N-Myc, MYCNOS, IGF2BP1, lncNB1, RNF217, RP11-102F4.3, GRIK3, and SLCO5A1 as the RNAs most considerably over-expressed in MYCN-amplified, compared with MYCN-non-amplified, neuroblastoma cell lines." (PMID 31690716, 2019).
Abdominal obesity (1 paper, 2019). Excessive fat around the stomach and abdomen. "The top four CpGs that were found to be differentially methylated between individuals with and without abdominal obesity were located at the genes c13orf36, ZC3H12D, MYO9B, and KCNG3 in females; and JPH3, TCP11L1, and GRIK3 in males (one CpG had no annotated gene)." (PMID 31212707, 2019).
autism (1 paper, 2025). Persistent deficits in social interaction and communication and interaction as well as a markedly restricted repertoire of activity and interest as well as repetitive patterns of behavior. "The GRIK gene family (GRIK1, GRIK2, GRIK3, GRIK4, and GRIK5) has genetic variants that contribute to various illnesses, including Huntington's disease, Parkinson's disease, autism, and schizophrenia." (PMID 41327126, 2025).
cocaine addicts (1 paper, 2022). "Alcoholics and cocaine addicts show upregulation of three genes relative to controls: Gria4, Grik3, and Grm4." (PMID 36362437, 2022).
colon cancer (1 paper, 2023). "For example, GRIK3 was reported to mediate the function of CircRNA and promote the proliferation and metastasis of colon cancer cells." (PMID 38099288, 2023).
diabetes (1 paper, 2014). "Having diabetes increases susceptibility to TB, and this may explain the GRIK1—GRIK3 interaction association we observed in the data." (PMID 25919455, 2014).
diabetic retinopathy (1 paper, 2025). "Furthermore, research has identified new links between the polymorphic loci in the GRIN1 gene (rs6293) and external eating behaviors in individuals with type 2 diabetes, as well as associations of the GRIK3 (rs534131) and GRIA1 (rs2195450) genes with diabetic retinopathy." (PMID 40740189, 2025).
glaucoma (1 paper, 2021). Increased pressure in the eyeball due to obstruction of the outflow of aqueous humor. "These 13 glaucoma-associated genes can be divided into three functional groups: phototransduction-related genes (GNGT1, OPN1SW, PDE6A, PDC, CRX, CNGB1, GUCY2F), glutamate receptor (GR) genes (GRIN2B, GRIK3, GRIK4), and 5-hydroxytryptamine receptor (HTR) genes (HTR1A, HTR1E, HTR7)." (PMID 33874942, 2021).
nematode infection (1 paper, 2019). "Two sub-units of NMDARS, NR2A and NR2B (also known as Grin2A and Grin2B) as well as several AMPARs including the metabotropic glutamate receptors 1 and 2 (mGlu-R1 and mGlu-R2), Gria3, Grm2, Grm4, Grik3 and Grik5 were up-regulated in the pup brain on P7 in response to maternal nematode infection." (PMID 30862816, 2019).
pituitary tumor (1 paper, 2024). A benign or malignant neoplasm affecting the pituitary gland. "Glutamate receptor kainate 3 (GRIK3) promotes epithelial-mesenchymal transition (EMT) in cancers, correlating with poor prognosis, and is overexpressed in GH-secreting pituitary tumors, indicating potential aggressiveness." (PMID 39139281, 2024).
prion disease (1 paper, 2023). A transmissible disease that is caused by a protein that is able to induce abnormal folding of normal cellular proteins, leading to characteristic spongiform brain changes, which are associated with neuronal loss without an inflammatory response. "The expression of GRIK3 was significantly correlated with pathways related to DNA replication, fatty acid metabolism, glyoxylate and dicarboxylic acid metabolism, linoleic acid metabolism, olfactory transduction, and prion diseases." (PMID 38099288, 2023).
psychosis (1 paper, 2019). "GRIK3 S310A, located in the amino terminal domain (ATD), was found to be protective against a broader neurodevelopmental phenotype, e.g. conditions with psychosis and ASD/ID phenotypes (p = 1.01 × 10−18; OR = 0.59, CI 0.52–0.66,)." (PMID 31844109, 2019).
cancer (8 papers, 2013 to 2025). A tumor composed of atypical neoplastic, often pleomorphic cells that invade other tissues. "Recent studies have suggested that GRIK3 may also play a role in cancer cell migration and invasion." (PMID 40149981, 2025). "Their co-clustering with the known genes of the Grik3 cluster suggests they may have a similar biological function, and are potentially involved in neurological diseases and different types of cancer." (PMID 38312938, 2024). "There is compelling evidence suggesting that GRIK3 participates in cancer progression." (PMID 38099288, 2023). "However, the precise mechanism by which GRIK3 expression influences cancer progression remains unclear." (PMID 30977227, 2019). "The expression of CHRNA3, GABRD, GRIK3, and GRIK5 in cancer cells significantly impacted their response to chemotherapy." (PMID 38099288, 2023). "Our analysis of drug sensitivity revealed that the expression of CHRNA3, GABRD, GRIK3, and GRIK5 in cancer cells significantly impacted their response to chemotherapy." (PMID 38099288, 2023).
tumor (5 papers, 2019 to 2024). "GRIK3, encoding the glutamate receptor, is crucial in synaptic transmission and implicated in tumor-related pathways like MAPK/ERK and mTOR." (PMID 38534332, 2024). "The CHRNA3, GABRD, GRIK3 and GRIK5 gene are associated with the sensitivity of certain anti-tumor drugs such as fluphenazine, pimozide, isotretinoin, and fludarabine." (PMID 38099288, 2023). "And results demonstrated that circASXL1 silencing obviously upregulated miR-1205 expression and downregulated GRIK3 protein expression in the neoplasms from sh-circASXL1 group." (PMID 34127015, 2021). "Protein expression analysis showed similar results, with higher GRIK3 levels in tumor tissue extracts." (PMID 30977227, 2019). "Furthermore, circASXL1 silencing hindered tumor formation by upregulating miR-1205 and downregulating GRIK3 expression." (PMID 34127015, 2021). "Therefore, all these data showed that circASXL1 absence repressed tumor growth via regulating miR-1205 and GRIK3 in vivo." (PMID 34127015, 2021). "Interestingly, GRIK3 was also involved in actin cytoskeleton regulation, indicating a possible role of GRIK3 in the morphologic change of tumor cells." (PMID 30977227, 2019). "Whether GRIK3 could switch some tumor phenotypes, such as cell proliferation, apoptosis, and metastasis, remains unclear." (PMID 30977227, 2019). "GRIK3 promotes cell proliferation and migration in vitro and tumor growth in vivo." (PMID 30977227, 2019). "Other studies have described that UBE2C, along with the other signaling molecules such as AURKA, EMT, GRIK3, CDK1, and claudin 19, activates the WNT/β-catenin signaling pathway, thus altering tumor biology." (PMID 39479352, 2024). "Results revealed that, compared to normal tissues, the expression of CHRNA3, GRIK3, and GRIK5 is decreased in tumor tissues, while GABRD is highly expressed in tumor tissues, consistent with our bioinformatics analysis results." (PMID 38099288, 2023). "The expression of GRIK3 at protein level was significantly higher in tumor tissues than in nontumor tissues (P < 0.001)." (PMID 30977227, 2019).
infection (1 paper, 2020). The state of being infected such as from the introduction of a foreign agent such as serum, vaccine, antigenic substance or organism. "GRIK3, glutamate receptor 7, is particularly interesting as glutamate is a chemotactic factor for neutrophils after injury or infection." (PMID 33059716, 2020).
neurodegenerative disease (1 paper, 2019). A disorder of the central nervous system characterized by gradual and progressive loss of neural tissue and neurologic function. "Glutamate Ionotropic Receptor Kainate Type Subunit 3 (GRIK3) is an important excitatory neurotransmitter receptor that plays a significant role in various neurodegenerative diseases." (PMID 30977227, 2019).
neurodevelopmental disorder (1 paper, 2025). A behavioral and cognitive disorder with onset during the developmental period that involves impaired or aberrant development of intellectual, motor, or social functions. "While we detail here the genetic and epigenetic mechanisms of Pvt1 ME and its functional consequence, there are several aME genes from our list that are associated with neurodevelopmental disorders, such as Grik3, Mettl5, Gap43, and Tubb3." (PMID 41223055, 2025).
GRIK3 also shares sentences with these, for which no sentence is quoted: colorectal cancer (4 papers); Anxiety (2); glioblastoma (2); neurological diseases (2); age-related hearing impairment (1); alcoholics (1); astrocytoma (1); attention deficit-hyperactivity disorder (1); bladder cancer (1); epilepsy (1); head and neck cancer (1); Insulin resistance (1); Intellectual disability (1); lung adenocarcinoma (1); mental disorder (1); multiple myeloma (1); pancreatic cancer (1); schizotypal personality disorder (1); staphylococcus aureus infection (1); thyroid tumor (1); type 1 diabetes (1); type 2 diabetes (1).